MAOA (monoamine oxidase A)
Diseases named in the same sentence as MAOA in open-access papers (continued):
Sharing a sentence is not in itself a finding about the gene and the disease.
pharyngeal cancers (5 papers, 2014 to 2025). "The MAOA (rs5906957) risk A-allele was significantly associated with the risks of oral and pharyngeal cancers (AOR = 1.67, 95% CI = 1.03–2.71) and OPMD (AOR = 2.55, 95% CI = 1.11–5.85)." (PMID 34209963, 2021). "Subjects with the MAOA (rs1137070) risk T-allele were significantly associated with the risks of oral cavity and pharynx cancers (AOR = 2.37, 95% CI = 1.47–3.81) and OPMD (AOR = 3.25, 95% CI = 1.43–7.38)." (PMID 34209963, 2021). "Compared with non-BQ chewers with MAOA rs3027452 (A-allele), BQ chewers with MAOA rs3027452 (G-allele) had a significantly synergistic risk of oral and pharyngeal cancers (AOR = 18.57; 95% CI, 5.06–68.18)." (PMID 34209963, 2021). "Moreover, the risk of oral cavity and pharynx cancers was much higher in carriers of the MAOA rs6323 G-allele and MAOB rs6324 G-allele." (PMID 39714760, 2025). "Furthermore, MAOA at-risk alleles (rs6323 [G], rs1137070 [T], or r5906957 [A]) were significantly responsible for the risk of oral and pharyngeal cancers and OPMD." (PMID 34209963, 2021). "Likewise, BQ chewers with MAOA rs1137070 (T-allele) had a significantly synergistic risk of oral and pharyngeal cancers (AOR = 36.22; 95% CI, 16.24–80.78) and risk of OPMD (AOR = 15.47; 95% CI, 4.67–51.26)." (PMID 34209963, 2021). "Subjects with the MAOA rs1137070 T-allele, MAOB rs6324 G-allele, and COMT rs4633 C/C-genotype had a significantly increased risk of oral and pharyngeal cancers (AOR = 78.62; 95% CI, 20.37–303.45)." (PMID 34209963, 2021). "Carriers of the MAOA rs6323 G-allele, MAOB rs6324 G-allele, and COMT rs4633 C/C-genotype had a prominently increased risk of oral cavity and pharynx cancers (AOR = 56.99; p < 0.001)." (PMID 34209963, 2021). "Subjects with MAOA rs1137070 (T-allele) and MAOB rs6324 (G-allele) had a significantly increased risk of oral and pharyngeal cancers (AOR = 45.56; 95% CI, 18.51–112.17) and risk of OPMD (AOR = 70.59; 95% CI, 14.17–351.78)." (PMID 34209963, 2021). "In terms of MAOA and COMT, subjects with MAOA rs6323 (G-allele) and COMT rs4633 (C/C genotype) had a significantly increased risk of oral and pharyngeal cancers (AOR = 2.94; 95% CI, 1.50–5.76) and risk of OPMD (AOR = 4.74; 95% CI, 1.54–214.57)." (PMID 34209963, 2021). "In terms of MAOA, MAOB, and COMT, subjects with the MAOA rs6323 G-allele, MAOB rs6324 G-allele, and COMT rs4633 C/C-genotype had a significantly increased risk of oral and pharyngeal cancers (AOR = 56.99; 95% CI, 15.82–205.31)." (PMID 34209963, 2021). "Subjects with MAOA rs1137070 (T-allele) and COMT rs4633 (C/C genotype) had a significantly increased risk of oral and pharyngeal cancers (AOR = 3.57; 95% CI, 1.86–6.82) and risk of OPMD (AOR = 5.31; 95% CI, 1.76–16.00)." (PMID 34209963, 2021). "With the exception of its role in neuropsychiatric symptoms and signs, no study has investigated the MAOA rs5953210 SNP as a genetic risk factor for the development of oral and pharyngeal cancers among individuals using BQ." (PMID 38392182, 2024). "Compared to non-BQ chewers with MAOA rs5906957 (G-allele), BQ chewers with MAOA rs5906957 (A-allele) had a significantly synergistic risk of oral and pharyngeal cancers (AOR = 24.15; 95% CI, 10.44–55.89) and risk of OPMD (AOR = 10.04; 95% CI, 2.83–35.56)." (PMID 34209963, 2021). "We assume that three biomarker (MAOA, MAOB, and COMT) variants may contribute to oral and pharyngeal cancers occurrence and may be implicated in the induction of arecoline." (PMID 34209963, 2021). "MAOA/COMT were implied to have roles in the susceptibility of oral and pharyngeal cancers." (PMID 34209963, 2021). "A similarly significant pattern was confirmed in the distribution of candidate genotypes of MAOA, MAOB, and COMT among men with oral cancer (n = 209), pharyngeal cancer (n = 88), and OPMD (n = 40), and controls (n = 193)." (PMID 34209963, 2021).
pharyngeal cancers (continued). "To confirm the differences in the distribution of MAOA, MAOB, and COMT among male patients with oral cancer (n = 209), pharyngeal cancer (n = 88), OPMD (n = 40), and control (n = 193), we divided the patients into four groups." (PMID 34209963, 2021). "Since arecoline plays a role in the inhibition of MAOA and is responsible for BQ dependence, we speculate that MAO and COMT may be involved in the development of oral and pharyngeal cancers." (PMID 34209963, 2021). "In particular, we found that BQ chewers with the MAOA (rs6323) risk G-allele had a significantly synergistic risk of oral and pharyngeal cancers (AOR = 31.15; 95% CI, 13.43–72.27) and OPMD risk (AOR = 12.77; 95% CI, 3.61–45.20) compared to non-BQ chewers with MAOA rs6323 (T-allele)." (PMID 34209963, 2021).
sleep disorder (5 papers, 2021 to 2024). A change from the patient's baseline sleeping pattern, in the hours slept and/or an alteration/dysfunction in the stages of sleep. "Moreover, bypass of melatonin synthesis, MAOA converts 5-HT into 5-hydroxyindoleacetic acid (5-HIAA; Reiter, 1991), which may lead to a sleep disorder, another type of non-motor symptom of PD." (PMID 33815093, 2021).
breast tumor (4 papers, 2019 to 2021). "Interestingly, MAOA transcript expression was also positively associated with resistance of breast tumor cell lines to both cytotoxic and targeted anticancer therapies." (PMID 34073226, 2021). "Moreover, like the expression of BTIC markers such as aldehyde dehydrogenase and CD44, increased MAOA transcripts expression is associated with reduced relapse-free survival in high-grade breast tumors of the TNBC clinical subtype." (PMID 34073226, 2021). "In silico mining of gene expression profiles of breast tumor cell lines that overexpressed individual components of RTK signaling pathways revealed that epidermal growth factor, a component of the chemically defined media required for sphere formation, increased the abundance of MAOA transcripts." (PMID 34073226, 2021).
gastric adenocarcinoma (4 papers, 2022 to 2026). "While ACLY expression is associated with advanced stage and prognosis in gastric adenocarcinoma, MAOA expression can promote the proliferation and metastasis of human gastric tumor cells by inducing mitochondrial dysfunction and aerobic glycolysis." (PMID 36090054, 2022).
Hodgkins lymphoma (4 papers, 2020 to 2025). A heterogeneous group of malignant lymphoid neoplasms of B-cell origin characterized histologically by the presence of Hodgkin and Reed-Sternberg (HRS) cells in the vast majority of cases. "In classical Hodgkin lymphoma, MAOA was expressed (181/241; 75%) by Hodgkin Reed–Sternberg (HRS) cells, with 34.8% showing strong expression." (PMID 34209963, 2021).
lung adenocarcinoma (4 papers, 2021 to 2025). A carcinoma that arises from the lung and is characterized by the presence of malignant glandular epithelial cells. "Our expression analysis revealed that CDH3, EDNRB, MAOA, and PLA2G1B matched our differential gene analysis results in IPF, Lung Adenocarcinoma (LUAD), and Lung Squamous Cell Carcinoma (LUSC) tissues." (PMID 40589973, 2025).
oral cancer (4 papers, 2014 to 2023). "An epidemiological study revealed that the use of antidepressants [e.g., MAOA inhibitors and selective serotonin reuptake inhibitors (SSRIs)] is associated with reduced risk of oral cancer occurrence." (PMID 37190117, 2023). "Compared to healthy controls, patients with risk polymorphisms of MAOA, MAOB, and COMT had a significantly enhanced risk of oral cancer." (PMID 34209963, 2021).
pancreatic ductal adenocarcinoma (4 papers, 2020 to 2024). An infiltrating adenocarcinoma that arises from the epithelial cells of the pancreas. "In a pancreatic ductal adenocarcinoma (PDAC) study, elevated levels of TPH1 and decreased levels of monoamine oxidase A (MAOA), a serotonin‐degrading enzyme, were reported, correlating with tumour stage, size and poor prognosis." (PMID 39223878, 2024).
psychosis (4 papers, 2014 to 2024). "For example, it was found that the relationship between maltreatment and antisocial behavior is modulated by the monoamine oxidase A (MAOA) genotype, while the catechol O-methyltransferase (COMT) genotype moderates the relationship between cannabis use and psychosis." (PMID 39457754, 2024).
behavioral disorders (3 papers, 2008 to 2022). "Three out of seven genes (i.e., HTR2C, MAOA, and OFD1) were previously associated with behavioral disorders in humans, such as aggressive behavior, antisocial personality, and low frustration tolerance." (PMID 33800722, 2021).
bladder cancer (3 papers, 2022 to 2026). "Our findings highlight MAOA as a potential tumor suppressor in bladder cancer, warranting further investigation as a therapeutic target." (PMID 41836296, 2026).
cardiac hypertrophy (3 papers, 2019 to 2023). "The data are consistent with former experiments in which deletion of MAOA in mice increased the plasma concentration of 5-HT, leading to excessive myocardial hypertrophy." (PMID 37371593, 2023). "Our study couples the expression of MAOA in the decompensated phase of myocardial hypertrophy to direct damaging effects of MAO-A activity." (PMID 37371593, 2023).
colorectal cancer (3 papers, 2020 to 2025). A primary or metastatic malignant neoplasm that affects the colon or rectum. "Downregulation of MAOA messenger (m)RNA levels was suggested as a biomarker for CRC, but neither the protein expression nor associations between MAOA and clinicopathological parameters in colorectal cancer have been addressed." (PMID 32316576, 2020). "Compared to MAOA, fewer studies have addressed the role of MAOB in cancer except for colorectal carcinoma (CRC), gliomas, PCa, and head and neck cancers, in which cases diverse roles were displayed." (PMID 41338163, 2025).
emotional dysregulation (3 papers, 2012 to 2026). "In our sample, the T/T genotype of MAOA rs1137070 was significantly associated with higher depressive symptoms, supporting its role in emotional dysregulation." (PMID 41460692, 2026).
fragile X syndrome (3 papers, 2014 to 2021). A genetic syndrome caused by mutations in the FMR1 gene which is responsible for the expression of the fragile X mental retardation 1 protein. "Here, we adopt this strategy to examine relationships between three SNPs (5-HTTLPR, MAOA, COMT) and specific clinically-relevant behaviours that are phenotypic of fragile X syndrome (FXS) but vary in severity and frequency across individuals." (PMID 32862204, 2021).
Hyperglycemia (3 papers, 2017 to 2023). An increased concentration of glucose in the blood. "To further strengthen the significance of our results, we investigated the effect of hyperglycemia on the expression of SERT, TPH1 and MAOA genes at ambient (21%) oxygen levels." (PMID 37371714, 2023). "Our results show similar effects of hyperglycemia when compared to either osmotic control or normoglycemic control (Figure A1), suggesting that the expression of SERT, TPH1 and MAOA was directly affected by high glucose, and not elevated osmotic pressure." (PMID 37371714, 2023).
liver fibrosis (3 papers, 2022 to 2024). "MAO exists as two isoenzymes, namely, monoamine oxidase A (MAO-A) and monoamine oxidase B (MAO-B), with the latter implicated in collagen fiber formation and closely associated with liver fibrosis." (PMID 38707500, 2024).
memory impairment (3 papers, 2007 to 2023). "Opposite to the down-regulation of GSTA1, GSTO1, and KEAP1, the BACE1 and MAOA proteins are elevated during the aging-associated memory impairment." (PMID 35767571, 2022). "Studies showed that BACE1 and MAOA proteins are strongly linked to aging-associated memory impairment." (PMID 35767571, 2022).
personality disorder (3 papers, 2019 to 2024). A diverse category of psychiatric disorders characterized by behavior that deviates markedly from the expectations of the individual's culture; this pattern of deviation is pervasive and inflexible and is stable over time. "Specifically, high levels of ACEs and high-activity MAOA genotype increased the levels of emotion dysregulation, which subsequently predicted higher levels of personality disorder." (PMID 35226575, 2023). "Two studies examined the interaction of MAOA genotype in the relationship between ACEs and personality disorders." (PMID 35226575, 2023). "Our results indicate that neuroticism might be regulated by MAOA and could be a common factor between different phenotypes, such as aggressive behaviors or personality disorders, observed in women with higher activity genotype who had been exposed to negative environments during childhood." (PMID 31448578, 2019).
pulmonary hypertension (3 papers, 2006 to 2023). Increased pressure within the pulmonary circulation due to lung or heart disorder. "It is interesting that while selective inhibition of MAOA ameliorated pulmonary hypertension, loss of both MAOA and MAOB caused the disease suggesting different functions for the two proteins in the pulmonary circulation." (PMID 34068984, 2021). "The upregulation of MAOA is of interest given the "serotonin" hypothesis of pulmonary hypertension." (PMID 16390543, 2006). "In the rat Sugen-hypoxia model of pulmonary arterial hypertension, a selective inhibitor of MAOA reduced oxidative stress in the pulmonary vasculature to normal levels and attenuated the development of pulmonary hypertension." (PMID 34068984, 2021).
Stroke (3 papers, 2021 to 2024). Sudden impairment of blood flow to a part of the brain due to occlusion or rupture of an artery to the brain. "This platform utilizes fluorescence imaging to simultaneously observe three critical indicators of the stroke, namely malondialdehyde (MDA), formaldehyde (FA), and monoamine oxidase A (MAO-A), providing high selectivity and sensitivity." (PMID 38672167, 2024).
substance dependence (3 papers, 2011 to 2022). The psychological or physiological need to take a substance in order to experience its effects or to avoid the effects of its absence. "It has been documented that the MAOA 4R allele influences the smoking habits of females, as well as nicotine dependence and smoking initiation for male smokers in a Japanese population." (PMID 21605465, 2011). "Given the nature of the sample, analyses were undertaken to determine whether substance dependence affected associations of sex and age with methylation levels of the MAOA ROI." (PMID 34424394, 2021). "MAOA gene is located on the short arm of the X chromosome, and some scholars found the genetic variation in MAOA effects on emotion, behavior and substance dependence." (PMID 36032227, 2022).
vitiligo (3 papers, 2018 to 2021). Generalized well circumscribed patches of leukoderma that are generally distributed over symmetric body locations and is due to autoimmune destruction of melanocytes. "The MAOA activity across the entire epidermis in patients with vitiligo increased by 5 to 10 times compared to skin in comparators of matching types." (PMID 34360837, 2021). "Defective catecholamine synthesis in the epidermis in vitiligo patients might increase NE levels with increased MAOA activity." (PMID 34360837, 2021). "In the present study, our analysis suggested that KBL might be of therapeutic effects on vitiligo by affecting catecholamine metabolism, neurotransmitter degradation (MAOA and MAOB), and intracellular steroid hormone receptor signaling pathway (ESR1)." (PMID 31781265, 2019). "The mRNA expression of DRD1 and DRD5, including GPX1, dopa decarboxylase (DDC), and monoamine oxidase A (MAOA), differs in vitiliginous skin, and the protein levels of DRD1, DRD5, DDC, MAOA, and MAOB vary in the skin and/or blood serum of patients with vitiligo." (PMID 34360837, 2021).
atherosclerosis (2 papers, 2012 to 2024). A disease characterized by the build-up of fatty material and calcium deposition in the arterial wall resulting in partial or complete occlusion of the arterial lumen. "This study investigates whether MAOA promoter methylation is associated with atherosclerosis, and whether this association is confounded by familial factors in a monozygotic (MZ) twin sample." (PMID 23116433, 2012).
Borderline personality disorder (2 papers, 2021 to 2023). A personality disorder characterized by impulsive behavior and unpredictable, capricious mood. "In a female only sample, high-activity MAOA genotype moderated the effect of ACEs on antisocial personality disorder and borderline personality disorder." (PMID 35226575, 2023).
COVID-19 (2 papers, 2021 to 2022). A disease caused by infection with severe acute respiratory syndrome coronavirus 2. "Significant concentration increases in severely affected COVID-19 patients is observed for both indolacetate and kynurenine as well as apparent increase in metabolising of serotonin in severe cases all part of tryptophan metabolism utilizing MAOA." (PMID 34017039, 2021). "Our results showed that SARS-CoV-2 infection did not affect the expression of DBH and VMAT2, but elevated, however, the mRNA levels of MAOA and MAOB in infected cells and in the whole blood samples of hospitalized COVID-19 patients." (PMID 36611805, 2022). "However, the mRNA levels of MAOA positively correlated with DDC in the blood samples of hospitalized COVID-19 patients, raising a question on the role of serum dopamine levels in these patients, as dopamine is a product of DDC and a substrate of MAOA enzymatic activities." (PMID 36611805, 2022). "The levels of LDH and FIB proteins in the blood samples of the hospitalized COVID-19 patients were the only in-hospital routinely measured laboratory parameters that had a moderate positive correlation with the expression of DDC, dACE2, and MAOA genes in this tissue." (PMID 36611805, 2022). "Similar to the DDC mRNA expression, the presence of comorbidities did not affect the mRNA levels of MAOA and MAOB in the whole blood samples of hospitalized COVID-19 patients." (PMID 36611805, 2022).
dyslexia (2 papers, 2018 to 2023). A learning disorder characterized by an impairment in processing written words. "KIAA0319, FOXP2, and DCDC2-KIAA0319 SNPs correlated with dyslexia; DCDC2-DYX1C1 SNPs associated with ADHD; COMT1, MAOA, DBH SNPs correlated with different dysfunctions." (PMID 36970271, 2023). "We examined 4 SNPs located on genes previously associated to dyslexia (KIAA0319, DCDC2, DYX1C1 and FOXP2) and 3 SNPs within genes related to ADHD (COMT, MAOA and DBH) in a cohort of Spanish children (N = 2078) that met the criteria of having one, both or none of these disorders (dyslexia and ADHD)." (PMID 30379906, 2018).
endometriosis (2 papers, 2023 to 2024). The growth of functional endometrial tissue in anatomic sites outside the uterine body. "GCH1, RPL8, PKLR, and MAOA were the key targets of paeonol in the treatment of endometriosis." (PMID 36677710, 2023).
fibromyalgia (2 papers, 2022 to 2023). A chronic disorder of unknown etiology characterized by pain, stiffness, and tenderness in the muscles of neck, shoulders, back, hips, arms, and legs. "DAP effectively averted fibromyalgia by downregulating monoamine oxidase-A (MAO-A), glutamate level, IL-1β, and TNF-α while elevating the GSH, dopamine, serotonin and norepinephrine levels." (PMID 36249766, 2022).